TGFB1 (transforming growth factor beta 1)
Diseases named in the same sentence as TGFB1 in open-access papers (continued):
Sharing a sentence is not in itself a finding about the gene and the disease.
Camurati-Engelmann disease (21 papers, 2011 to 2025). Camurati-Englemann disease (CED) is a rare, clinically variable bone dysplasia syndrome characterized by hyperostosis of the long bones, skull, spine and pelvis, associated with severe pain in the extremities, a wide-based waddling gait, joint contractures, muscle weakness and easy fatigability. "In humans, gain-of-function mutations in TGFB1 are associated with Camurati-Engelmann disease, characterized by sclerosis of long bones and cranial bones; mice carrying the same Tgfb1 mutation exhibit similar phenotypes observed in humans." (PMID 39941080, 2025). "Camurati–Engelmann Disease (CED), or Progressive Diaphyseal Dysplasia, is a rare autosomal dominant disorder caused by heterozygous mutations in the TGFB1 Gene, essential for bone regeneration." (PMID 39596554, 2024). "Disrupting the TGFβ1 gradient in mice with an activating Tgfb1 mutation recapitulates Camurati-Engelmann disease, characterized by disorganized stromal cell recruitment, dysplastic bones, and increased risk of fracture." (PMID 36656634, 2023). "Gain-of-function mutations in TGFB1 predispose to diaphyseal dysplasia, and mutations in other TGFβ superfamily members can cause multiple skeletal disorders of varying severity." (PMID 36653343, 2023). "Camurati-Engelmann disease (CED) is a sclerosing bone dysplasia caused by transforming growth factor β1 (TGFB1) gene variants." (PMID 36339419, 2022). "A total of 7/47 probands suspected with OI carried variants in 6 disease-causing genes, namely, 1 IFITM5, 1 CRTAP, 2 BMP1, 1 PLS3, and 1 COL1A2 (c.432 + 4_432 + 7delAGTA was ignored previously), and 1 case of Camurati-Engelmann disease with pathogenic variants in TGFβ-1, which was misdiagnosed." (PMID 34557487, 2021). "Camurati-Engelmann disease (progressive diaphyseal dysplasia) (MIM131300) results from a gain-of-function mutation in Transforming Growth Factor Beta-1 (TGFB1), resulting in thickened diaphyseal cortices, increased BMD, limb pain, fatigability, muscle weakness and a waddling gait." (PMID 33193107, 2020). "We report a 32-year-old man and his 59-year-old mother with a unique and extensive variant of Camurati-Engelmann disease (CED) featuring histopathological changes of osteomalacia and alterations within TGFβ1 and TNFSF11 encoding TGFβ1 and RANKL, respectively." (PMID 21541994, 2011). "Camurati-Engelmann disease (CED, MIM #131300), also called progressive diaphyseal dysplasia (PDD), is a rare autosomal dominant skeletal disorder that belongs to the group of sclerosing bone dysplasia, the pathogenic gene of which is the transforming growth factor β1 (TGFB1)." (PMID 36339419, 2022). "Human disease associated with mutations in the RANKL gene is rare, although a novel mutation in the gene for transforming growth factor beta 1 (TGFβ1) and a missense change in TNFSF11 encoding RANKL may both contribute to the bone phenotype associated with Camurati-Engelmann disease." (PMID 24278766, 2013).
cognitive decline (21 papers, 2013 to 2025). "Propolis also increased levels of TGFβ1, which correlated with protection against cognitive decline compared to the placebo group, highlighting its anti-inflammatory and neuroprotective effects." (PMID 40333577, 2025). "The specificity of the cognitive deficits that we observe in Tgfb1 Het and Tgfb1 cKO mice suggests that age-related changes in microglia-derived TGFB1 predominantly impacts hippocampal-dependent cognitive decline." (PMID 38645176, 2024).
Sjögren’s syndrome (21 papers, 2009 to 2025). "It has been reported that a pathological decrease in TGFβ-1 (along with decreased IL-1 receptor antagonist) levels may contribute to mucosal damages such as oral erosions associated with infections as also seen in Sjögren Syndrome." (PMID 33673258, 2021).
Thrombocytopenia (21 papers, 2009 to 2026). A reduction in the number of circulating thrombocytes. "This could be due to thrombocytopenia caused by increased platelet removal by the enlarged spleens, as the levels of TGFβ1 substantially reflect the levels released from platelets during venipuncture and the processing of the blood samples." (PMID 19149774, 2009).
age-related macular degeneration (20 papers, 2012 to 2025). Age-related loss of vision in the central portion of the retina (macula), secondary to retinal degeneration. "High TGFβ1 levels promote vascularization of normally avascular ONL of photoreceptors, a condition known as retinal angiomatous proliferation (RAP), which is a subset of age-related macular degeneration (AMD)." (PMID 32080187, 2020).
dengue (20 papers, 2012 to 2025). "The activity boost was compatible with the higher TGFβ1 levels for the peripheral group at dengue onset." (PMID 29255469, 2017). "Host variations in TGFβ1-mediated switch to a more diversified profile of IgA effectors could be a novel contributing factor to dengue hemorrhages." (PMID 29255469, 2017). "Indeed shortly after dengue onset the peripheral group had much higher TGFβ1 levels than the central group (p< 0.029, U test)." (PMID 29255469, 2017).
periodontal disease (20 papers, 2010 to 2025). "The high abundance of TGFB1 in dogs with dental calculus associated with the presence of Rho GTPase pathway is a relevant finding that may suggest, for futher investigations, TGFB1 as a biomarker candidate of periodontal disease in this species." (PMID 32814559, 2020). "In particular, ASU has shown efficacy against periodontal disease by modulating the expression of transforming growth factor beta 1 (TGF-β1), TGF-β2, and bone morphogenetic protein 2 (BMP-2)." (PMID 31554332, 2019). "SDD also exhibits certain essential characteristics that may impede the evolution of periodontal disease, such as inhibition of MMPs, inhibition of the degranulation of polymorphonuclear (PMN) cells, and increased production of TGFβ1." (PMID 38533160, 2024).
Pleural effusion (20 papers, 1997 to 2024). The presence of an excessive amount of fluid in the pleural cavity. "We treated SUM159, BT549 (both established from primary tumor), MDA-MB-231, and MDA-MB-436 (both derived from pleural effusion) with TGFβ1 and, 8h later, the NDRG1 gene was knocked down for 48h (8+48 protocol)." (PMID 36594086, 2023). "In the same way, soft-agar colony formation provided similar findings as only knockdown of NDRG1 with TGFβ1 led to a reduced number of colonies in primary-tumor- and pleural-effusion-derived cell lines." (PMID 36594086, 2023). "Indeed, it has been observed that TGFB1 levels in pleural effusion are higher in S-MPMs as compared with E-MPMs and have strong prognostic values." (PMID 37460925, 2023). "Hence, we studied whether NDRG1 could have a differential role on EMT upon TGFβ1 stimulation by western blot in primary-tumor- or pleural-effusion-derived cell lines." (PMID 36594086, 2023).
abdominal aortic aneurysm (19 papers, 2013 to 2026). Enlargement and ballooning of the vessel that supplies arterial blood to the abdomen, pelvis and legs. "Other research indicated the increased risk of abdominal aortic aneurysm for individuals with the TGFB1 rs1800469 TT genotype compared with the CC genotype." (PMID 35307021, 2022). "One study has demonstrated that interactions between TGFB1 gene polymorphism and environmental factors promoted abdominal aortic aneurysm." (PMID 35307021, 2022).
aortic stenosis (19 papers, 2009 to 2026). Aortic valve stenosis is a aortic valve disease caused by the incomplete opening of the aortic valve. "High shear conditions promote increased release and activation of platelet-derived TGFβ1 both in vitro and in mouse models of aortic stenosis." (PMID 35355968, 2022). "Progression of AS in murine models is attenuated by the knockout of platelet TGFβ1, supporting a key role of shear-induced TGFβ1 release and of platelets in general in the pathogenesis of aortic stenosis." (PMID 35355968, 2022).
esophageal adenocarcinoma (19 papers, 2007 to 2025). A malignant tumor with glandular differentiation arising predominantly from Barrett mucosa in the lower third of the esophagus. "The expression of TGFBRII and TGFB1 is lower in oesophageal adenocarcinoma (EAC) compared to normal oesophagus." (PMID 39648148, 2024).
migraine (19 papers, 2013 to 2025). "TGFB1 at chr19q13.2 (lead SNP rs1800470, PCPASSOC = 1.49 × 10−17 based on SHet statistic) was shared between migraine and PP alone and encodes a transforming growth factor-beta 1 protein (TGF-β1) family member." (PMID 32632093, 2020). "Our DEPICT gene analysis also prioritized TGFB1 at the novel 19q13 migraine-associated locus." (PMID 34294844, 2021). "Early works suggested that TGFB1 could play a role in migraine susceptibility." (PMID 34294844, 2021). "Among them, Alb, Tgfb1, Icam1, CD4, and Ptprc are explicitly or potentially implicated in immune-inflammatory and oxidative stress mechanisms involved in migraine pathophysiology." (PMID 40699640, 2025). "In this study, we identified that NTG-induced migraine is associated with the PI3K–Akt signaling pathway, cytokines and their receptor interactions, and nine key hub genes (Alb, Tgfb1, Cd4, Ptprc, Itgb1, Icam1, Col1a1, Pxdn, and Itgad) through transcriptomics." (PMID 40699640, 2025). "Another study investigated the TGFB1 genotype in pediatric migraine patients and reported significant differences between control and migraine patients." (PMID 34294844, 2021). "In this study, transcriptomic analysis revealed significant downregulation of Alb and upregulation of Tgfb1, Icam1, CD4, and Ptprc in NTG-induced migraine model rats." (PMID 40699640, 2025).
gastric adenocarcinoma (18 papers, 2015 to 2025). "In summary, we report here that metastases‐prone gastric adenocarcinoma patients show higher frequency of TGFB1 SNPs associated with lower TFG‐β1 production." (PMID 33274798, 2021). "Therefore, we speculate that TGFβ1 promoted M2c macrophage metabolites are closely associated with ferroptosis resistance in gastric adenocarcinoma TME." (PMID 39991579, 2025). "The results of a large dataset from TCGA and GEO confirm that the content of TGFβ1 in gastric adenocarcinoma is higher than that in normal gastric tissue." (PMID 39991579, 2025). "Conversely, high MIR100HG and TGFB1 expression correlated with poor survival outcome in stomach adenocarcinoma." (PMID 33941855, 2021). "Four TGFB1 SNPs and TGF‐β1 production by stimulated PBMC were determined in seventy‐eight gastric adenocarcinoma patients." (PMID 33274798, 2021). "TGFβ1 has shown potential research value in the study of gastric adenocarcinoma and TME 61-64." (PMID 39991579, 2025). "The probiotic anti-H. pylori activity using the well diffusion test, its immunomodulatory activity was measured using transforming growth factor beta 1 (TGF-β1) cytokine production by human gastric adenocarcinoma (AGS) cells, and its viability was measured using the microdrop technique." (PMID 35159484, 2022). "According to the boxplot analysis, the mRNA levels of DOCK4, GNAS, TGFB1, SELE, and SMARCE1 demonstrated a considerably higher expression in gastric adenocarcinoma than in healthy controls." (PMID 37037466, 2023). "Further analysis of clinical features revealed a negative correlation between the expression of TGFβ1 and the survival time of gastric adenocarcinoma patients, and a high correlation between TGFβ1 and T staging." (PMID 39991579, 2025). "However, our extensive research and data in gastric adenocarcinoma do not support the view that TGFβ1 inhibits tumor growth 74-76." (PMID 39991579, 2025).
hepatitis C (18 papers, 2012 to 2025). "Corilagin has also been reported to cause the release of TNF-α inhibitor in inflammation, decrease the secretion of the transforming growth factor beta 1 (TGF-β1) in a dose dependent manner, and inhibit hepatitis C viral replication in vitro." (PMID 30609707, 2019).
lymphopenia (18 papers, 2012 to 2025). Reduction in the number of lymphocytes. "At month three, LC patients had elevated IL10RB and MCP-1, whereas by month six, levels of several proteins (monocyte chemoattractant proteins MCP2/CCL8 and MCP4/CCL13, lymphopenia associated IL2RB, and TGF-signaling LAP/TGFb1) had fallen." (PMID 40572685, 2025). "SIID is typified by lymphopenia, increased levels of anti-inflammatory cytokines such as IL-10 and transforming growth factor beta 1 (TGF-β), and splenic atrophy." (PMID 31281252, 2019).
meningioma (18 papers, 2000 to 2025). A generally slow growing tumor attached to the dura mater. "We noticed that genes such as TGFBI, SNAI1, MMP2, TGFB1, TGFB2, IGFBP7, and LTBP2 were upregulated by the treatment of M2-MDEs in meningioma cells and may contribute to tumor invasion and proliferation behavior." (PMID 35637794, 2022).
papilloma (18 papers, 2010 to 2024). A benign epithelial neoplasm that projects above the surrounding epithelial surface and consists of villous or arborescent outgrowths of fibrovascular stroma. "Transgenic overexpression of TGFβ1 in papillomas is associated with up-regulated matrix metalloproteinase (MMP) expression, loss of membrane-associated E-cadherin/catenin complex and increased angiogenesis." (PMID 21297902, 2010). "Similarly, benign papillomas with a high risk progression phenotype exhibit reduced expression of TGFβ1." (PMID 23326666, 2012). "However, loss of TGFβ1 immunostaining in papillomas has been correlated with an increased risk of malignant conversion." (PMID 21297902, 2010). "On the other hand, TGFβ1 overexpression after papilloma establishment stimulated malignant transformation and metastasis." (PMID 37887285, 2023). "As TGFβ1 inhibits the proliferation of epithelial cells, TGFβ1 overexpression prior to tumor formation suppressed benign papilloma formation in transgenic mice." (PMID 37887285, 2023). "In DBMA/TPA-treated mouse skin, TGFβ1 is upregulated in basal cells in papillomas and inhibits cell proliferation and papilloma formation, whereas carcinoma cells are devoid of TGFβ1 expression." (PMID 36003785, 2022). "In an inducible transgenic model, induction of TGFβ1 expression after papilloma development promotes progression to carcinomas that metastasize to lymph nodes." (PMID 21297902, 2010). "Surprisingly, TPA treatment alone induced papilloma formation suggesting that inhibition of TGFβ1 signaling in some cells could act as an initiating event." (PMID 23326666, 2012). "Overexpression of TGFβ1 in the epidermis blocks TPA-induced hyperplasia and papilloma formation and Tgfb1−/− keratinocytes transduced with a v-RasHa retrovirus rapidly form SCC in athymic mouse skin grafts, while Tgfb1+/+ keratinocytes develop only benign papillomas." (PMID 23326666, 2012). "Two-stage carcinogenesis experiments with transgenic mice that overexpress TGFβ1 in the epidermis via either K6 or K10 promoters results in formation of fewer papillomas, but increased conversion to carcinomas and progression to aggressive spindle cell carcinomas with elevated TGFβ3 expression." (PMID 21297902, 2010). "Hence, our data indicating significantly higher levels of TGFβ1 in Itga11-/- papillomas than in Itga11+/+ papillomas suggest that enhanced TGFβ1 signaling could be one reason for the reduced tumor cell proliferation and impaired primary tumor growth." (PMID 36003785, 2022). "To test this, we removed the iLCs from the papillomas and incubated them overnight in supporting medium containing GMCSF and TGFβ1." (PMID 32210959, 2020). "Here, TGFβ1 overexpression in late-stage papillomas with wildtype Type II receptor did not inhibit proliferation but increased metastasis and EMT." (PMID 23326666, 2012). "We observed a similar influx of DC into papillomas expressing TGFβ1, although these were not characterized as completely." (PMID 23326666, 2012).
alopecia (17 papers, 2014 to 2026). Hair loss usually from the scalp. "The down-regulation of TGFB1 in the giant panda may imply their partial responsibility for giant panda alopecia." (PMID 35413801, 2022). "This article aims to reviewthe fibrogenic activity of TGFβ1, its control by PPAR and its relationwith DHEA in the frontal fibrosing alopecia." (PMID 28099600, 2016).
cleft palate (17 papers, 2013 to 2025). Cleft palate is a fissure type embryopathy that affects the soft and hard palate to varying degrees. "Topiramate treatment of primary MEPM cells also increased expression of SRY-Box Transcription Factor 9 (SOX9), a TGFB1 target that causes cleft palate when abnormally expressed." (PMID 33577554, 2021). "For instance, pathogenic variants in the TGFB1 and TGFB3 genes are linked to the development of cleft lip and cleft palate, conditions that are frequently observed in individuals with LDS." (PMID 40282317, 2025).
gastritis (17 papers, 2010 to 2026). Inflammation of the stomach. "Furthermore, in the gastric mucosa of the patients with H. pylori-infected gastritis, USP15, ZNF451, TGFB1, and CCNT were identified as participants in the TGF-β signaling pathway, while FYB, HLA-DRB1, ANKRD24, and TMEM35 were implicated in T lymphocyte differentiation and immune response processes." (PMID 41035878, 2025).
gout (17 papers, 2014 to 2025). A condition characterized by painful swelling of the joints, which is caused by deposition of urate crystals. "As a first exploration, mRNA levels of TGFB1, TGFBRI, TGFBRII and three TGF-β target genes ITGAV, MMP9 and SMAD7 were compared between untreated adherent monocytes of patients with gout and age and sex matched healthy controls." (PMID 36850003, 2023). "Expression levels of TGFB1 were increased in individuals with gout compared to controls, and ITGAV mirrored this expression of TGFB1." (PMID 36850003, 2023).
keratoconus (17 papers, 2011 to 2025). A degenerative, structural disorder of the eye, characterized by a cone-shaped protrusion of the cornea. "Other genes like VSX1, SOD1, TGFb1, MIR184, COL4A3/4, RAB3GAP1, LOX, HGF and DOCK9, are also identified in association with keratoconus." (PMID 33923743, 2021). "The genetic risk factors have been researched genome-wide, among which the corneal dystrophy genes ZEB1 and TGFb1 are considered to be related to keratoconus." (PMID 33923743, 2021). "Other candidate genes including SOD1, ZEB1, TGFB1, FLG, interleukin, and collagen may have a role to play in the pathogenesis of keratoconus and need further elucidations." (PMID 25254113, 2014).
left ventricular hypertrophy (17 papers, 2010 to 2025). Enlargement of the LEFT VENTRICLE of the heart. "Sorafenib inhibited both the rise in TGFβ1 and collagen in cardiac tissue, thus preventing the essential component of left ventricular hypertrophy, i.e. interstitial collagen deposition." (PMID 24885948, 2014). "The distribution of the T29C TGFβ1 gene polymorphism was analyzed in 198 hypertensives with left ventricular hypertrophy (LVH) and in 235 hypertensives without LVH." (PMID 20981300, 2010).
oral submucous fibrosis (17 papers, 2015 to 2026). "In contrast, in our study on naringenin's antifibrotic effects in oral submucous fibrosis (OSMF) focuses on molecular targets such as MMP2, MMP3, MMP9, TGFB1, ESR1, and SERPINE1, which are crucial in ECM remodeling and inflammation." (PMID 40575446, 2025).